GLO1 (glyoxalase I)
Diseases named in the same sentence as GLO1 in open-access papers (continued):
Sharing a sentence is not in itself a finding about the gene and the disease.
autism (12 papers, 2007 to 2025). Persistent deficits in social interaction and communication and interaction as well as a markedly restricted repertoire of activity and interest as well as repetitive patterns of behavior. "On the other hand, the A allele is more prevalent in individuals with autism, which leads to reduced activity of the Glo1 enzyme in brain extracts and results in the accumulation of advanced AGEs in the damaged brain." (PMID 38027126, 2023). "Nonetheless, some human-genome-related studies (GWAS) have been unable to determine the correlation between GLO1 polymorphism and autism, and further studies should explore the functional significance." (PMID 36432007, 2022). "Human studies have indicated that the coding of single-nucleotide polymorphisms (SNPs) in GLO1 is associated with autism." (PMID 36432007, 2022). "As reported in other papers and through the SAFRI autism candidate gene database, Glo1 mutations are highly related to autism, a neurodevelopmental disorder." (PMID 36414636, 2022). "One clinical study even reported an association between the C419 allele, instead of A419, and autism, and found lower GLO1 enzymatic activity in autistic patients with the C419 allele than in those with A419." (PMID 34953453, 2022). "Human studies have proposed an association between a coding SNP in GLO1 (419A/C; rs2736654) and autism." (PMID 23181072, 2012). "A subsequent study partially replicated this finding by showing evidence that the 111A allele of GLO1 confers protection from autism in unaffected siblings." (PMID 19266052, 2009). "The 111E allele was reported to be significantly more common in autism patients versus controls and there was also a decrease in GLO1 enzymatic activity in autistic brains." (PMID 19266052, 2009). "The A111E GLO1 protein variant, encoded by SNP C419A, was identifed in autopsied autistic brains and proposed to act as an autism susceptibility factor." (PMID 17346350, 2007). "A C419A single nucleotide polymorphism (SNP) (reported in dbSNP as rs2736654 or rs4746; NM_006708.3:c.332A>C, p.Glu111Ala) present in GLO1, which causes an Ala111Glu substitution in the protein, has been reported to be associated with panic disorder and autism." (PMID 34953453, 2022). "A recent study on prenatal treatment with valproic acid (VPA) in a mouse model of autism showed enhanced GLO1 expression and reduced MG levels in the brain." (PMID 34953453, 2022). "Similarly, the mechanism underlying GLO1's putative involvement in autism remains unknown." (PMID 23181072, 2012). "These initial studies yielded promising evidence supporting TPH2 and GLO1 roles as autism vulnerability genes." (PMID 17346350, 2007). "Interestingly, a prior study showed that inhibiting GLO1 using pBBG increased social interaction in a murine autism model." (PMID 40412584, 2025). "The presence of 410 A/C SNP and its effect on autism in mice can show whether GLO1 may be a contributing factor to autism." (PMID 36432007, 2022). "Furthermore, GLO1 inhibitors ameliorated the autism-like phenotype in VPA-treated mice through GABAA stimulation by MG." (PMID 34953453, 2022). "Alternatively, it is possible that GLO1's role in GABAergic signaling could contribute to autism since disruptions in GABAergic signaling have been identified in autism." (PMID 23181072, 2012). "GLO1 gene variants do not confer autism vulnerability in this sample, but allele A419 apparently carries a protective effect, spurring interest into functional correlates of the C419A SNP." (PMID 17346350, 2007). "In addition, the possibility that the decreased GLO1 activity observed in patients with autism reflects secondary effects of the onset of autism may need to be considered." (PMID 34953453, 2022). "Experimental studies in mice may help determine whether GLO1 is related to autism-like behaviors." (PMID 23181072, 2012).
autism (continued). "The present study provides evidence that TPH2 and GLO1 gene variants do not contribute significantly to autism pathogenesis in our sample, while GLO1 could seemingly exert a protective effect in unaffected siblings." (PMID 17346350, 2007).
leukemia (10 papers, 2010 to 2025). A malignant (clonal) hematologic disorder, involving hematopoietic stem cells and characterized by the presence of primitive or atypical myeloid or lymphoid cells in the bone marrow and the blood. "When used in conjunction with doxorubicin (DOX), troglitazone was shown to cause synergistic cell death in a resistant leukemia cell line that expressed high levels of GLO-1." (PMID 20454582, 2010). "The use of BrBzGSHCp2 has been proven to be effective both in vitro and in vivo models where Glo1 is expressed at high levels, as demonstrated in lung cancer cell line and mouse model, in drug resistant leukemia cells and in Huh7 HCC cell line." (PMID 33869040, 2021). "In human leukemia cells, GLO1 is involved in apoptosis resistance to antitumor agents and the use of GLO1 inhibitors prepare the cells to chemotherapeutic agents." (PMID 29321821, 2017). "This Glo-1 inhibitor has been shown to increase the sensitivity of human leukemia cells to anti-tumor agents." (PMID 24978626, 2014). "A synthetic inhibitor of GLO-1 sensitized chemoresistant leukemia cells over-expressing the enzyme to chemotherapy, and this compound has shown significant antiproliferative effects when used on tissue xenografts in small animals." (PMID 20454582, 2010). "Furthermore, the competitive GLO1 inhibitor ethyl pyruvate (EP) showed specific antitumor activity in leukemia cell lines, mainly by depleting cancer cell ATP reserves without impairing normal cell function." (PMID 40352588, 2025). "In Bcr-Abl+ leukemia, hypoxia-adapted (HA)-Bcr-Abl+ cells exhibiting stem cell-like characteristics showed higher GLO1 expression and enzymatic activity, and GLO1 inhibitors effectively suppressed the viability and capacity for tumor formation of this HA-Bcr-Abl+ cells." (PMID 30559934, 2018). "Moreover, high GLO1 expression has been observed in a variety of human cancers, including leukemia and cancers of the lung, stomach, colon, pancreas, liver, prostate, oropharynx, skin and breast." (PMID 30559934, 2018).
colorectal cancer (8 papers, 2016 to 2025). A primary or metastatic malignant neoplasm that affects the colon or rectum. "Specifically we showed that high tumor MG adducts accumulation is associated with low GLO1 expression and activity levels and increased aggressiveness in colorectal cancer patients." (PMID 28117708, 2017). "A potential role for GLO-1 in the progression of colorectal cancer has also been indicated in other studies." (PMID 40727469, 2025). "The expression of selected genes related to MG degradation III (AKR1B10, AKR1C2 and ADH4), glyoxalase system (GLO1 and HAGH), glucose transport (SLC2A1 and SLC5A1) and colorectal cancer-associated genes (AREG, CXCL8 and CEACAM1) were quantitated using qRT-PCR." (PMID 32561807, 2020). "In colorectal cancer (CRC) and anaplastic thyroid cancer (ATC) tissues, MG adduct levels adducts are positively correlated with tumor malignancy and metabolic activity, and the oncogenic effects of MG can be effectively reversed by MG scavengers or GLO1 agonists." (PMID 40352588, 2025).
diabetic neuropathy (8 papers, 2012 to 2024). A chronic, pathological complication associated with diabetes mellitus, where nerve damages are incurred due to diabetic microvascular injury involving small blood vessels that supply these nerves, resulting in peripheral and/or autonomic nerve dysfunction. "While genetic polymorphisms of Glo2 are extremely rare, different SNPs (single nucleotide polymorphisms) have been identified in the Glo1 gene and found to be associated with reduced enzyme activity, increased prevalence of diabetic neuropathy, and increased risk of cardiovascular complications." (PMID 28106778, 2017). "On the other hand, the increased frequency of the CC genotype of the GLO1 gene (rs2736654 or rs4746) has been reported in patients with diabetic neuropathy." (PMID 38928135, 2024). "On the other hand, hesperidin shows excellent potential as a biomolecule for treating diabetic neuropathy, with its neuroprotective effects achieved through enhancing Glo-1 and inhibiting the AGEs/ RAGE interaction via Nrf-2/ARE pathway activation." (PMID 38234970, 2023). "We previously reported that MIF can aggravate diabetic neuropathy by suppressing glyoxalase I and intraepidermal nerve fibers on the footpad skin." (PMID 34445689, 2021). "Strain dependent differences in Glo1 copy numbers also confirm that a lower expression of Glo1 promotes the development of diabetic neuropathy symptoms." (PMID 28106778, 2017). "Our results show that sustained elevations of endogenously formed MG by pharmacological inhibition of GLO-1 leads to the development of a painful diabetic neuropathy-like condition in mice." (PMID 24167592, 2013). "Together, these findings suggest a role for GLO1 in mediating behavioral measures of pain, particularly that related to diabetic neuropathy." (PMID 23181072, 2012). "MIF has been suggested to aggravate diabetic neuropathy by suppressing glyoxalase-I." (PMID 34831154, 2021).
dyslipidemia (7 papers, 2016 to 2025). "While both female and male Glo1+/− mice show evidence for dyslipidemia at 28 weeks, the metabolic phenotypes manifested are sex-dependent." (PMID 39896461, 2025). "Thiamine decreased body weight and improved glycemia, insulin function, dyslipidemia, and activity of glyoxalase-I in MS rats with anti-glycation, antioxidant, and anti-inflammatory activities." (PMID 33995940, 2021). "In conclusion, correlation analysis of data from the HATFF study indicates that the responses of optimised Glo1 inducer, tRES-HESP, are linked to improvements in dysglycemia, blood pressure, dyslipidemia, and low-grade inflammation." (PMID 34371884, 2021). "Glo-1 is a driver of cardiovascular disease, likely through dicarbonyl stress-driven dyslipidemia and vascular cell dysfunction." (PMID 27406712, 2016). "If confirmed, fructose restriction and GLO1 inducers and/or dietary components may cooperate to ease the current metabolic syndrome and MASLD outbreaks." (PMID 40430220, 2025). "This suggests increasing Glo1 expression may have health benefits through decreasing vascular inflammation and improving hemodynamics and dyslipidemia." (PMID 34371884, 2021). "Moreover, it attenuated dyslipidemia, glucotoxicity, and histological changes through the Glo1 and Nrf2 pathway." (PMID 30223524, 2018).
type 1 diabetes (7 papers, 2014 to 2024). "The enzymatic activity, protein levels, and mRNA levels of Glo-1 were examined to investigate its role in the neuroprotective function of hesperidin in type 1 diabetes." (PMID 32982741, 2020). "In the OVE26 mouse model of type 1 diabetes, it was shown that RAGE deficiency reduced glomerulosclerosis, improved renal function and this was accompanied by decreased MG and increased GLO1 expression." (PMID 24920125, 2014). "The same Glo1 transgenic mice were treated with streptozotocin (STZ) to induce type 1 diabetes." (PMID 33255888, 2020).
neuropathy (6 papers, 2016 to 2024). A disorder affecting the nervous system that manifests with pain, tingling, numbness, and/or muscle weakness. "A recent study comparing the expression of GLO1 in various inbred mouse strains showed a negative correlation between GLO1 expression and mechanical hyperalgesia, implying that GLO1 might be linked to painful neuropathies." (PMID 34887734, 2021).
breast tumors (5 papers, 2009 to 2018). "On one hand, the search for copy number changes on a large set of cancer cell lines revealed that GLO1 is amplified in many types of human cancer with breast tumors (22%) and sarcomas (17%) showing the highest rates." (PMID 27759563, 2016). "It has been reported that Glo-1 expression and activity are increased in breast tumor cells, most likely to control the high MG level spontaneously produced due to high glycolytic activity." (PMID 24978626, 2014). "No doubt that the validation of GLO1 as a target for cancer therapy will need a better characterization of those breast tumors that are more likely to be sensitive." (PMID 27759563, 2016). "Glo-1 expression was significantly higher in Her-2 positive breast tumors when compared with Her-2 negative ones." (PMID 24978626, 2014).
Cognitive impairment (5 papers, 2022 to 2025). Abnormal cognition is characterized by deficits in thinking, reasoning, or remembering. "Our results suggest that screening for adverse cognitive changes in patients receiving brain-penetrant GLO1 inhibitors will be critical, as there may be the possibility of cognitive impairment." (PMID 41100182, 2025). "In the present study, KK-Ay mice displayed cognitive impairment, with glucose elevation, AGEs accumulation, oxidative stress, insulin resistance, reducing the contents of GLO1 protein, NADPH, or GSH, and MG (a major precursor of AGEs) hyperactivity in the brain or plasma." (PMID 37259448, 2023). "Moreover, while we were completing our study, it has been published that circulating neuronal EVs from mild cognitive impairment and different stages of Alzheimer’s disease patients contain Glo1." (PMID 36009243, 2022). "Furthermore, overexpression of GLO1 in the hippocampus of chronically stressed mice reduced MGO levels, mitigating CUMS-induced neuroinflammation and cognitive impairment." (PMID 40136646, 2025).
colon cancer (5 papers, 2010 to 2025). "In accordance with these observations, in vivo experiments using GLO1-depleted HCT116 colon cancer cells showed an increased tumor growth associated with MG adducts accumulation that can be reverted by carnosine, a potent MG scavenger." (PMID 28117708, 2017). "In line with our previous study, we show here that GLO1 depletion in colon cancer cells induces an increased level of argpyrimidine adducts and enhanced tumor growth in vivo." (PMID 28117708, 2017). "Interestingly, however, the overexpression of Glo1 in human colon tumors has previously been reported." (PMID 20184735, 2010). "A recent study also showed that the combination of MG and silencing of glyoxalase I (GLO1), the enzyme responsible for MG detoxification, can inhibit in-vitro SW620 colon cancer as well as in-vivo SW620 colon cancer xenograft model in mice." (PMID 32561807, 2020).
diabetic retinopathy (5 papers, 2014 to 2025). "Studies have shown that tanshinone IIA can improve the mitochondrial dysfunction and mitosis induced by advanced glycation end products by increasing the level of GLO1, thus improving the damage of retinal endothelial cells caused by diabetic retinopathy." (PMID 32963574, 2020). "In bovine retinal endothelial cells, bovine retinal pericytes, and an animal model, candesartan attenuated vascular damage in diabetic retinopathy by restoring Glo1 activity and mRNA for Glo1 to at least control levels." (PMID 38067472, 2023). "In this regard, it has also been reported that the angiotensin type 1 receptor blocker, candesartan, prevents angiotensin II‐induced downregulation of GLO1 and that this may contribute to its ability to protect against diabetic retinopathy." (PMID 24920125, 2014). "A mouse study suggests that TRPC channels play a role in the accumulation of MGO, with the subsequent TRPC knockout mice protected against diabetic retinopathy, having lower MGO levels and increased GLO1 activity." (PMID 40722867, 2025).
epilepsy (5 papers, 2017 to 2024). A brain disorder characterized by episodes of abnormally increased neuronal discharge resulting in transient episodes of sensory or motor neurological dysfunction, or psychic dysfunction. "Differences in GLO1 expression and activity can influence epilepsy susceptibility via modulation of the concentration of endogenous MGO in the brain." (PMID 36432007, 2022). "In addition, GLO1 polymorphisms are significantly related to epilepsy." (PMID 29556176, 2018). "Although there are no clinical reports showing an association between alcoholism/sleep disorder and GLO1, a clinical study reported that rs1049346 T>C SNP in 5′-UTR of GLO1 was associated with late-onset epilepsy and drug-resistant epilepsy." (PMID 34953453, 2022). "Epileptic seizures were theoretically alleviated in animal epilepsy models in which GLO1 activity was reduced, resulting in insufficient clearage of MG." (PMID 29556176, 2018). "Meanwhile, GLO1 suppression reduces seizures, indicating that this may be a novel therapeutic approach for epilepsy." (PMID 36432007, 2022). "To date, dual regulation of miRNAs has been demonstrated in many pathological conditions, such as ovarian injury and apoptosis, which raised a profound question as to whether miRNAs could improve epilepsy by targeting both GLO1 and RAGE." (PMID 29556176, 2018). "This study systematically reviewed the significance of GABAergic MG, glyoxalase I (GLO1; responsible for enzymatic catalysis of MG cleavage) and downstream RAGE signaling in epilepsy." (PMID 29556176, 2018). "However, miRNAs have not been reported to target both GLO1 and RAGE, and their roles in epilepsy remain unknown." (PMID 29556176, 2018).